DMD (dystrophin)
Diseases named in the same sentence as DMD in open-access papers (continued):
Sharing a sentence is not in itself a finding about the gene and the disease.
muscular dystrophy (continued). "A Norfolk terrier was referred to the Animal Health Trust neurology department with suspected dystrophin-deficient muscular dystrophy (DD-MD), which was confirmed by clinical workup and immunohistochemistry." (PMID 26401335, 2015). "We show that normal muscular activity in vivo is a main factor for initiating structural changes in both dystrophin and laminin α2-chain associated muscular dystrophy in the zebrafish larvae." (PMID 26536238, 2015). "Dystrophin forms an essential link between sarcolemma and cytoskeleton, perturbation of which causes muscular dystrophy." (PMID 26459831, 2015). "Mutations in the gene that encodes Dystrophin can cause several different types of muscular dystrophy, a group of diseases in which muscle progressively weakens." (PMID 26459831, 2015). "Female 10-006C had spastic right hemiplegia (GMFCS II) and a paternally inherited duplication affecting part of the X-linked DMD muscular dystrophy gene, which is predicted to be likely benign." (PMID 26236009, 2015). "We have examined effects of immobilization in larvae from two zebrafish strains with muscular dystrophy, the Sapje dystrophin-deficient and the Candyfloss laminin α2-chain-deficient strains." (PMID 26536238, 2015). "Mutations in dystrophin, DG, or several enzymes that glycosylate α-DG underlie severe forms of human muscular dystrophy." (PMID 26319583, 2015). "The main underlying objective was to analyze in parallel the primary abnormality in muscular dystrophy and the many secondary changes triggered by the deficiency of dystrophin." (PMID 28248273, 2015). "Immunohistochemical analysis of sarcolemmal proteins in muscle biopsies like dystrophin, SGCs, merosin, and dysferlin is an important part of the diagnostic evaluation of patients with muscular dystrophy." (PMID 25050186, 2014). "Defects in components of the dystrophin–glycoprotein complex (DGC) are known to be an important cause of different forms of muscular dystrophy." (PMID 25221510, 2014). "The expression of N-glycolylneuraminic acid (Neu5Gc) and the cytotoxic T cell (CT) carbohydrate can impact the severity of muscular dystrophy arising from the loss of dystrophin in mdx mice." (PMID 24505439, 2014). "Second, zebrafish represent excellent models of human muscular dystrophies, in particular loss of Dystrophin to model DMD 10,11,12." (PMID 24459606, 2013). "These mice, deficient for both dystrophin and the dystrophin-related protein utrophin, display a more severe, progressive form of muscular dystrophy as compared with the mdx mice." (PMID 23618411, 2013). "BackgroundDuchenne muscular dystrophy is a lethal, progressive, muscle-wasting disease caused by mutations in the DMD gene." (PMID 24292657, 2013). "In the field of muscular dystrophy, striated muscle function is often assessed in vitro in dystrophin-deficient mdx mice in order to test the impact of a potential treatment strategy." (PMID 23162469, 2012). "Several papers reported that oxidative stress is implicated as a pertinent factor involved in pathogenesis of dystrophin-mutated muscular dystrophies." (PMID 23251671, 2012). "In this report, we demonstrate that the serum levels of several muscle-specific miRNAs are increased in two dystrophin-deficient muscular dystrophy animal models." (PMID 21479190, 2011). "The mdx mice bear a naturally occurring mutation in exon 23 of the dystrophin gene that abrogates expression of the full-length dystrophin protein, causing symptoms of muscular dystrophy." (PMID 21603573, 2011). "The dystrophin gene, DMD, a gene whose mutations underlie most muscular dystrophies, was underexpressed as compared to healthy muscle in all but one patient (patient 4) and scored a mean 0.37 as the tm-score." (PMID 21453538, 2011). "In the present work using mouse models, we have further demonstrated that a double-deficiency in both dystrophin and dysferlin results in more severe muscular dystrophy." (PMID 22132688, 2011).
muscular dystrophy (continued). "Mutations in the genes coding for either dystrophin or dysferlin cause distinct forms of muscular dystrophy." (PMID 22132688, 2011). "Here, we demonstrate that the serum levels of several muscle-specific miRNAs are increased in the dystrophin-deficient muscular dystrophy mouse model, mdx, as well as the canine X-linked muscular dystrophy in Japan dog model (CXMDJ)." (PMID 21479190, 2011). "Loss of the DGC from the sarcolemma causes membrane instability, which is the primary defect of dystrophin-deficient muscular dystrophy." (PMID 21552523, 2011). "Here we describe the severe phenotype, histopathological findings, and molecular analysis of Cavalier King Charles Spaniels with dystrophin-deficient muscular dystrophy (CKCS-MD)." (PMID 20072625, 2010). "In muscle, α-catulin controls the localization of the dystrophin complex, a multimeric protein complex implicated in muscular dystrophy." (PMID 20865173, 2010). "Given that proteins affecting components of the dystrophin complex are likely to contribute to the pathogenesis of muscular dystrophy, α-catulin is a candidate causal gene for a form of muscular dystrophy in humans." (PMID 20865173, 2010). "Research into mini-gene (truncated) therapeutic constructs for gene restoration is currently underway for other genes associated with muscular dystrophy such as dystrophin, whose size exceeds the 5kb AAV vector packaging limit." (PMID 20667140, 2010). "In summary, we have described the clinical phenotype and revealed the genetic cause of dystrophin deficient muscular dystrophy in a group of CKCS: a deletion in the region of the dystrophin gene that is most commonly mutated in DMD." (PMID 20072625, 2010). "In this study we sought to determine the genetic basis of dystrophin-deficient muscular dystrophy in 3 CKCS dogs." (PMID 20072625, 2010). "Two additional young male CKCS from the USA were also diagnosed with dystrophin deficient muscular dystrophy (dogs 2 and 3)." (PMID 20072625, 2010). "Research on DMD has benefited from the availability of mdx mice, in which a naturally occurring mutation in exon 23 of the dystrophin gene abrogates expression of the full-length dystrophin polypeptide, causing symptoms reminiscent of muscular dystrophy." (PMID 19277212, 2009). "The mdx mouse model of muscular dystrophy has a nonsense mutation in exon 23 of the dystrophin gene." (PMID 16719929, 2006). "The mdx mouse has a nonsense mutation in exon 23 of the dystrophin gene and has been used as an animal model of dystrophin mutations and muscular dystrophy." (PMID 16719929, 2006). "Notably, application of carbonic anhydrase inhibitors displayed a therapeutic potential in two animal models of dystrophin deficient muscular dystrophy." (PMID 38652110, 2024). "It is estimated that up to 7.8% of females harboring mutations in the DMD gene are manifesting carriers, developing symptoms that may range from mild muscle weakness to a rapidly progressive DMD-like muscular dystrophy." (PMID 36911943, 2023). "Muscular dystrophy is a disease of the muscles caused by mutations in the dystrophin-encoding gene." (PMID 37514158, 2023). "Mutations in proteins such as dystrophin and caveolin, which together with other proteins form structural connections between the cytoskeleton and the extracellular matrix, are frequently the culprit of muscular dystrophies." (PMID 36909082, 2023). "Several studies have used the mdx dystrophin deficient mouse, the most used animal model of the destructive human dystrophin deficient muscular dystrophy DMD, to study the chronic effects of oral administration of NAC in drinking water or by intraperitoneal injection on skeletal muscle pathology." (PMID 36866174, 2023). "Our analysis identified a rare variant in DMD causing muscular dystrophy in the patient." (PMID 37298193, 2023).
muscular dystrophy (continued). "The role of the Dp71 dystrophin isoform in muscular dystrophy progression and the mechanisms underlying its upregulation in the presence of truncated dystrophin remain unclear." (PMID 37298068, 2023). "We report a large single-centre study on the spectrum of DMD gene variants observed in 750 patients analyzed for suspected Duchenne (DMD) or Becker (BMD) muscular dystrophy, over the past 30 years, at the Cardiomyology and Medical Genetics of the University of Campania." (PMID 36672955, 2023). "Mutations in the dystrophin gene, or DAPs genes, result in a wide range of muscular dystrophies." (PMID 36505053, 2022). "Loss-of-function variants in the dystrophin gene, a well-known cause of muscular dystrophies, have emerged as a mutational risk mechanism for autism spectrum disorder (ASD), which in turn is a highly prevalent (~ 1%) genetically heterogeneous neurodevelopmental disorder." (PMID 37861890, 2022). "Similar results were observed in a DMD Drosophila model, the muscular dystrophy model with the deletion in the gene encoding sarcoglycan (Sgcd) that is a key component for maintaining muscle membrane integrity along with dystroglycan and dystrophin." (PMID 35330385, 2022). "The recently created del52hDMD/mdx mouse model, genetically and functionally characterized, which carries both murine (with stop mutation in exon 23) and human (with deletion of exon 52) DMD genes, exhibits muscular dystrophy and shows impaired muscle function." (PMID 35563191, 2022). "Thus, while both dystrophin and dysferlin are expressed in the endothelium and are associated with the development of muscular dystrophies, they play vastly different roles in vascular homeostasis and indeed the progression of vascular disease." (PMID 34366880, 2021). "Therefore, cardiovascular cells derived from muscular dystrophy patients’ induced pluripotent stem cells are well suited to mimic dystrophin-associated cardiomyopathy and hold great promise for the development of future fully effective therapies." (PMID 32977524, 2020). "To begin to understand whether and how myonuclear heterogeneity is altered in muscle disease, we conducted snRNAseq on Mdx fibers (1939 nuclei), a mouse model of muscular dystrophy caused by mutation of the Dystrophin gene." (PMID 33311457, 2020). "However, the severity of muscular dystrophies is associated with pathogenic variants in DMD, which encodes the protein dystrophin." (PMID 31923192, 2020). "The identification of dystrophin nucleated the study of the membrane cytoskeleton of myofibers, with the subsequent work on the dystrophin‐associated glycoprotein complex and other types of muscular dystrophies associated with components of this complex creating a fertile field of discovery." (PMID 32608079, 2020). "While mutations in DMD have typically been associated with muscular dystrophy, loss of dystrophin has recently been associated with aggressive behavior in human cancers with and without myogenic programs, suggesting it may have tumor suppressor functions." (PMID 31341965, 2019). "Autophagy is reported to be impaired in muscular dystrophies, and the activation of autophagy by low-amino-acid intake ameliorates the skeletal muscle phenotype of mouse models of muscular dystrophies including dystrophin-deficient mdx mice, a model of DMD9,10." (PMID 30348945, 2018). "Mutations in the dystrophin gene lead to muscular dystrophy of Duchenne or Becker type." (PMID 28095895, 2017). "There is evidence from dystrophin-deficient mouse models that increasing levels of utrophin at the muscle fibre sarcolemma by genetic or pharmacological means significantly reduces the muscular dystrophy pathology." (PMID 26974331, 2016). "Indeed, fiber type remodeling is reported in dystrophin-deficient muscular dystrophies, including the mild mdx mouse model and a canine model, which for the most part describe an increase in oxidative fiber types with disease." (PMID 27430020, 2016).
muscular dystrophy (continued). "Notably, Jag1 overexpression rescued the muscular dystrophy phenotype of dystrophin-deficient zebrafish." (PMID 27644105, 2016). "Disruption of membrane stability due to the loss of dystrophin-glycoprotein complex (DGC) or membrane repair capacity due to the defect in dysferlin has been widely reported to be responsible for various types of muscular dystrophies." (PMID 26693275, 2015). "The major findings of this study indicate that muscle-specific expression of IGF-1 (mIGF-1) can counter aspects of the muscular dystrophy associated with the loss of dystrophin, modulating relevant molecules of the genetic and epigenetic circuitries in the mdx dystrophic mouse model." (PMID 25999854, 2015). "Since dystrophin interacts with a complex of other proteins and glycoproteins, it is possible to compensate for dystrophin deficiency using them as potential point of therapeutic attack, as postulated in the development of new treatments for muscular dystrophies." (PMID 26544626, 2015). "Therefore, muscular dystrophy except for dystrophin deficiency induces the enhancement of myostatin-dependent signaling." (PMID 25221510, 2014). "Indeed, loss of both dystrophin and utrophin in double knockout (mdx/Utrn-/-) mice leads to a much more severe muscular dystrophy than observed in mdx mice." (PMID 23951345, 2013). "Indeed, mutations that abrogate expression of dystrophin or impair binding of α-dystroglycan to the extracellular matrix lead to usually severe forms of muscular dystrophy associated with myofiber degeneration." (PMID 23951345, 2013). "The LGMD patients in our study, although not having been diagnosed with specific genetic defects, had a family history of affected siblings and were positive for dystrophin immunostaining, distinguishing them from the more common form of muscular dystrophy, X-linked Duchenne’s muscular dystrophy." (PMID 24204966, 2013). "Duchenne (DMD) and Becker (BMD) muscular dystrophies are X-linked allelic disorders caused by mutations in the dystrophin gene, which may result in the absence (DMD) or a defective (BMD) muscle protein dystrophin." (PMID 22707356, 2012). "Our data suggest that leaky RyR1 channels may underlie multiple forms of muscular dystrophy linked to mutations in genes encoding components of the dystrophin-glycoprotein complex." (PMID 22640601, 2012). "To confirm this hypothesis, we quantified the expression levels of miRNAs in serum of the dystrophin-deficient muscular dystrophy mouse model, mdx, and the canine X-linked muscular dystrophy in Japan dog model (CXMDJ), by real-time PCR." (PMID 21479190, 2011). "Mouse studies suggested that utrophin may serve as a functional substitute for the dystrophin gene and can be viewed as a rescue protein in muscular dystrophy caused by abnormal dystrophin expression." (PMID 20950417, 2010). "An automated process has been developed for the detection of deletions, duplications/insertions and point mutations in any gene or family of genes and has been applied to ten genes known to bear mutations that cause muscular dystrophy: DMD; CAV3; CAPN3; FKRP; TRIM32; LMNA; SGCA; SGCB; SGCG; SGCD." (PMID 19835634, 2009). "DMD is a plasma membrane-associated cytoskeletal protein of the spectrin superfamily and its absence or functional deficiency is the cause of several types of muscular dystrophies in humans." (PMID 20019881, 2009). "Additionally, initial evidence of activated necroptosis in dystrophin-deficient mouse and human muscles shows how preventing this type of programmed cell death could be a potential therapeutic tool to improve muscular dystrophies." (PMID 35177651, 2022). "Out-of-frame dystrophin mutations or premature stop-codon mutations typically lead to complete loss of the dystrophin protein and are more severe, while in-frame mutations that lead to the synthesis of a partially functional truncated protein produce milder forms of muscular dystrophy, such as BMD." (PMID 36237531, 2022).
muscular dystrophy (continued). "This was shown to impair sarcolemmal integrity and render dystrophin-deficient fibers more susceptible to membrane rupturing, which in turn triggers abnormal ion homeostasis and impaired signaling, affecting especially calcium handling and excitation-contraction coupling in muscular dystrophy." (PMID 36362832, 2022). "Also, overexpression of PGC1α ameliorates muscular dystrophy in dystrophin-deficient mice." (PMID 28367954, 2017). "Hence, dystrophin deficiency and the resulting collapse of the linkage between the intracellular actin cytoskeleton and the basal lamina triggers a variety of downstream modifications in muscular dystrophy." (PMID 24917816, 2014). "In addition to muscular dystrophies, mutations in human dystrophin can cause dilated cardiomyopathy, rhabdomyolosis and a malignant hyperthermia-like reaction in response to inhaled anesthesia, supporting the conclusion that this locus causes the observed phenotypes in pigs." (PMID 22691118, 2012). "Overall, the efficacy of DMD gene editing often leads to higher dystrophin restoration than the level considered to exert a therapeutic effect, although the required level of dystrophin restoration sufficient to prevent muscular dystrophy remains debated." (PMID 41328300, 2025). "Casimersen, eteplirsen and golodirsen are RNA therapeutics that promote exon skipping in dystrophin, thereby halting the progression of muscular dystrophy." (PMID 41166051, 2025). "Monogenic mutations in other subunits of the DAPC can also directly affect dystrophin function, leading to various types of muscular dystrophies, including certain forms of LGMDs." (PMID 39949979, 2025). "Alternatively, the codon‐optimized miniaturized utrophin, which serves as the autologous homologue of dystrophin, has been reported to prevent the muscular dystrophy phenotype in mouse and dog models." (PMID 39949979, 2025). "For the Duchenne muscular dystrophy gene DMD (rs1545663, rs5927867), a clear role in the pathogenesis of several cancers was reported." (PMID 40831500, 2025). "Viral vector optimization efforts demonstrate particular promise, exemplified by AAV-mediated delivery of miniaturized dystrophin constructs achieving functional recovery in canine muscular dystrophy models with negligible adverse events." (PMID 40255230, 2025). "Several porcine models of DMD, such as the DMD ΔEx52 pig, the DMD ΔEx27 Chinese Diannan pig, or the DMD mEx13, have been described and exhibited a severe muscular dystrophy similar to human DMD but suffered from a faster disease progression." (PMID 38786024, 2024). "Muscle biopsy showed clear features of muscular dystrophy, and immunohistochemical analysis suggested reduced expression of dystrophin." (PMID 39461972, 2024). "Recent progress using distinct clock mutant animal models crossed with mdx mice, a pre-clinical dystrophin-deficient model for DMD, established the genetic basis for circadian clock interventions to mitigate the disease pathophysiology of muscular dystrophies." (PMID 38731986, 2024). "Dystrophinopathies belong to the large spectrum of muscular dystrophies and present a variable involvement of skeletal and cardiac muscles; they are due to mutations in the DMD gene, which encodes the dystrophin protein." (PMID 38791328, 2024). "For example, DMD, which is the most common muscular dystrophy, was found to contain exon deletion (65%), duplications (10%), or smaller-scale mutations (25%) in different regions of the DMD gene." (PMID 38607035, 2024). "Mice lacking the cytoplasmic portion of Dystroglycan that interacts with Dystrophin develop muscular dystrophy but exhibit largely normal brain development." (PMID 39257744, 2024). "Systemic administration of AAV9s delivering CBE and sgRNA designed to skip exon 4 in DmdE4 mice resulted in efficient dystrophin restoration and rescue of muscular dystrophy phenotype." (PMID 38786024, 2024).